CUX1 (cut like homeobox 1)
Diseases named in the same sentence as CUX1 in open-access papers (continued):
Sharing a sentence is not in itself a finding about the gene and the disease.
autoimmune disease (1 paper, 2013). A disorder resulting from loss of function or tissue destruction of an organ or multiple organs, arising from humoral or cellular immune responses of the individual to their own tissue constituents. "The induction of CUX1 proteins could be therapeutic for preventing acute and chronic inflammatory diseases, such as septic shock or autoimmune diseases." (PMID 23805228, 2013).
Cachexia (1 paper, 2021). Severe weight loss, wasting of muscle, loss of appetite, and general debility related to a chronic disease. "While mice injected with Flt3ITD cells remained healthy during this study, recipients of Cux1+/−;Flt3ITD cells developed pallor and cachexia which compromised their survival." (PMID 33931647, 2021).
cartilage disorders (1 paper, 2025). "Furthermore, the CUX1 gene mutation, identified as the underlying cause of the patient’s neurodevelopmental disorder, has not previously been linked to any bone or cartilage disorders." (PMID 39852205, 2025).
diabetic foot ulcers (1 paper, 2023). "It should be noted that other regulatory factors, such as lncRNA SNHG16 and circ-CUX1 which have been reported as miR-16-5p regulators, might modulate the expression of miR-16–5 in wound healing in the diabetic foot ulcers." (PMID 37098476, 2023).
dilated cardiomyopathy (1 paper, 2024). Cardiomyopathy which is characterized by dilation and contractile dysfunction of the left and right ventricles. "scGO also identified CUX1, SOX6, and SVIL, which have been reported as pivotal factors implicated in causing dilated cardiomyopathy." (PMID 39820437, 2024).
dystroglycanopathy (1 paper, 2024). "To compare cortical migration across our five models of dystroglycanopathy, we performed immunostaining for the upper layer marker Cux1 (layers II/III-IV) and the deep layer marker Tbr1 (layers III, VI) in P30 somatosensory cortex." (PMID 38179984, 2024).
hypothyroidism (1 paper, 2021). Abnormally low levels of thyroid hormone. "Therefore, the morphogenetic abnormalities observed in hypothyroidism may result from hypoactivity of CUX1." (PMID 33762687, 2021).
idiopathic pulmonary fibrosis (1 paper, 2016). Idiopathic pulmonary fibrosis (IPF) is a nonneoplastic pulmonary disease that is characterized by the formation of scar tissue within the lungs in the absence of any known cause. "Here we show that CUX1 isoforms are localized within α-smooth muscle actin-positive cells in SSc skin and idiopathic pulmonary fibrosis (IPF) lung tissue sections." (PMID 27583344, 2016).
inflammatory bowel disease (1 paper, 2020). A spectrum of small and large bowel inflammatory diseases of unknown etiology. "CUX1 is implicated in inflammatory bowel disease and various cancer types, although primarily due to loss‐of‐function somatic mutations." (PMID 32615015, 2020).
insulinomas (1 paper, 2020). "CUX1 expression was also linked to recurrence and disease-related death in human insulinomas, demonstrating a strong prognostic impact." (PMID 32707646, 2020). "Furthermore, CUX1 expression is strongly associated with a less differentiated phenotype and short survival in patients with breast cancer, and is correlated with the malignant and metastatic phenotype of insulinomas." (PMID 32707646, 2020). "Previously, we identified the transcription factor CUX1 as mediator of tumour aggressiveness in insulinomas." (PMID 32707646, 2020). "In insulinomas, CUX1 enhanced tumour progression by stimulating proliferation and angiogenesis in vitro and in vivo." (PMID 32707646, 2020). "Based on our previous data in resected benign and malignant insulinomas we have established a histological scoring system for CUX1 using an immunoreactivity score (IRS) with a cut-off value of 8 determined by ROC analysis (AUC 0.74, p = 0.006)." (PMID 32707646, 2020). "Recently, we identified the homeodomain transcription factor Cut homeobox 1 (CUX1) as mediator of tumour de-differentiation and metastatic behaviour in human insulinoma patients." (PMID 32707646, 2020).
ischemia (1 paper, 2013). A hypoperfusion of the BLOOD through an organ or tissue caused by a PATHOLOGIC CONSTRICTION or obstruction of its BLOOD VESSELS, or an absence of BLOOD CIRCULATION. "In this model, there is deep layer-selective neuronal cell death, such as Ctip2-positive deep-layer neurons, in contrast to preserving Cux1-positive superficial-layer neurons from the medial to the lateral side after ischemia." (PMID 23970853, 2013).
Leukoencephalopathy (1 paper, 2020). This term describes abnormality of the white matter of the cerebrum resulting from damage to the myelin sheaths of nerve cells. "Cux1 is a transcriptional factor associated with axonal projection and the numbers of Cux1+ neurons are reduced in CSF1R-related leukoencephalopathy patients compared to age-matched controls." (PMID 33287883, 2020).
lung adenoma (1 paper, 2014). A benign, well circumscribed epithelial neoplasm that arises from the bronchus or the lung parenchyma. "Experiments in primary human and rodent cells suggested that CUX1 increases the number of lung adenomas, when expressed together with KRASG12V, by reducing oxidative DNA damage and preventing cell senescence." (PMID 24618719, 2014).
lung squamous cell carcinoma (1 paper, 2022). "In lung squamous cell carcinoma (LUSC), suppressed tumoral LAG-3 expression is linked to mutations in Cut Like Homeobox 1 (CUX1), FA Complementation Group A (FANCA), or NOTCH4 genes." (PMID 36077354, 2022).
macrocytic anemia (1 paper, 2021). Anemia that is characterized by increased red blood cell volume. "Blood from 10-week-old Cux1+/−;Flt3ITD mice revealed macrocytic anemia, neutrophilia and monocytosis." (PMID 33931647, 2021). "In contrast, haploinsufficient Cux1+/fl;Vav-iCre+ (referred to as Cux1+/−) mice displayed mild macrocytic anemia without significant abnormalities in absolute leukocyte numbers, although myelodysplastic features were evident in blood and bone marrow cytospins." (PMID 33931647, 2021).
Marfan syndrome (1 paper, 2020). A disorder of the connective tissue. "Previous studies have also shown that an increase in TGF-β signalling in Marfan syndrome can suppress type I collagen production via the induction of the transcription factor CUX1." (PMID 32173378, 2020).
metastatic disease (1 paper, 2020). "While CUX1 did not correlate with clinical or pathological parameters, such as age, sex or SMS-positivity, it was associated with more wide-spread extrahepatic and extra-lymphatic metastatic disease (e.g., bones, lung, peritoneal or spleen) (p = 0.021)." (PMID 32707646, 2020).
migraine (1 paper, 2021). "Overall, these findings support that CUX1 is functionally involved in migraine." (PMID 34380431, 2021).
periodontitis (1 paper, 2022). An acute or chronic inflammatory process that affects the tissues that surround and support the teeth. "Among these results, some genes associated with periodontitis compared to microarray dataset, FACR, and CUX1." (PMID 36233348, 2022).
prostate tumours (1 paper, 2016). "In Pten-null prostate tumours and human cancer cells, we found manifold increase in p110 CUX1 isoform and an undetectable level of p200 CUX1 when compared with the control." (PMID 27941799, 2016).
rheumatoid arthritis (1 paper, 2021). A chronic, systemic autoimmune disorder characterized by inflammation in the synovial membranes and articular surfaces. "A recent study revealed that transcription factor CUX1, a known tumor suppressor, is a key regulator of inflammation in rheumatoid arthritis." (PMID 33563285, 2021).
scleroderma (1 paper, 2016). Scleroderma is a rare autoimmune connective tissue disorder characterized by abnormal hardening of the skin and, sometimes, other organs. "Further, in the scleroderma (SSc) lung and diffuse alveolar damage lung sections, CUX1 localized within the α- smooth muscle actin (α-SMA) positive cells, “High doses of TGF-beta potently suppress type I collagen via the transcription factor CUX1”." (PMID 27583344, 2016).
Splenomegaly (1 paper, 2021). Abnormal increased size of the spleen. "In addition, splenomegaly was evident in Cux1+/−;Flt3ITD mice." (PMID 33931647, 2021).
Stroke (1 paper, 2024). Sudden impairment of blood flow to a part of the brain due to occlusion or rupture of an artery to the brain. "We analyzed the expression of neuronal subtype-specific transcription factors CUX1 (upper-layer neurons, layers 2/3) and CTIP2 (lower-layer projection neurons, layers 5/6) at PSD63 in R26R-YFP mice that received Neurod1 post-stroke." (PMID 38540276, 2024).
thymic atrophy (1 paper, 2025). "At necropsy, both Cux-1- and WSFL24-infected chickens exhibited thymic atrophy compared to controls." (PMID 41340930, 2025).
thymoma (1 paper, 2025). A neoplasm arising from the epithelial cells of the thymus. "The most frequently mutated genes within each subtype were as follows: PCLO (27%), POT1 (27%), and STAT3 (27%) in idiopathic PRCA; STAT3 (20%), DNMT3A (10%), and CUX1 (10%) in thymoma-associated PRCA; and STAT3 (54%) and TET2 (12%) in LGLL-associated PRCA." (PMID 40202536, 2025).
thyroid cancer (1 paper, 2023). "Interestingly, SNPs associated with thyroid cancer (THCA) in three THCA driver genes were found to be under positive selection in the East Asian population (CUX1 and RGPD3) and the European population (HERC2)." (PMID 37098512, 2023). "Moreover, SNPs associated with thyroid cancer in three thyroid cancer driver genes (CUX1, HERC2 and RGPD3) were under positive selection in East Asian and European populations, consistent with the high incidence of thyroid cancer in these populations." (PMID 37098512, 2023).
viral infection (1 paper, 2024). "After viral infection, downregulation of CUX1 was first confirmed by both Western blot and qPCR analyses (Lane 2 and 3)." (PMID 38944813, 2024).
tumor (77 papers, 2007 to 2026). "Cux1 is involved in the polarization of tumor-associated macrophages by antagonizing NF-κB signaling." (PMID 40223093, 2025). "Mutations in APC, AXIN1, and CUX1 are known to promote tumor aggressiveness, stemness, and metastatic dissemination." (PMID 40842629, 2025). "CUX1 (CUT-like homeobox 1) is identified as a haploid tumor suppressor associated with both tumor inhibition and progression." (PMID 39103807, 2024). "CUX1, encoding a homeodomain-containing transcription factor, is recurrently deleted or mutated in multiple tumor types." (PMID 34997000, 2022). "Aberrant expression of KRT8 is associated with multiple tumor progression and metastasis; so is CUX1." (PMID 35428183, 2022). "This mutation in CUX1 results in increased tumor growth and increased susceptibility to PI3K-Akt inhibition." (PMID 35546872, 2022). "Altered levels and mutations of the CUX1 transcription factor have been implicated in cancer across several tumor types and species." (PMID 34997000, 2022). "CUX1 has also been implicated in the regulation of proteosome-mediated degradation of the Src tyrosine kinase resulting in altered tumor cell migration and invasion." (PMID 35546872, 2022). "Based on these data, we aimed to examine which CUX1 variant was predominantly responsible for the observed tumor-promoting phenotype in KCCux1 mice." (PMID 34070180, 2021). "The transcription factor CUX1 has been implicated in either tumor suppression or progression, depending on the cancer entity and the prevalent CUX1 isoform." (PMID 34070180, 2021). "Although underexpressed CUX1 promotes tumor development, overexpression of CUX1 is associated with advanced cancers." (PMID 32619008, 2020). "In the RIP1Tag2 mouse model, CUX1 expression was associated with advanced tumour stage and resistance to apoptosis." (PMID 32707646, 2020). "In the cancers of the large intestine, copy number variation analysis evidenced that frequent copy number gain of CUX1 was observed and associated with tumor aggressiveness." (PMID 33014778, 2020). "Among all 32 putative target genes of miR-193a-5p, we identified four tumor-associated genes, including CUX1, ITSN1, OLA1, and RAP2A." (PMID 33014778, 2020). "In summary, we demonstrate that elevated CUX1 and its generated circ‐CUX1 are associated with poor outcome of NB patients, and exert oncogenic roles in aerobic glycolysis and tumor progression." (PMID 31709724, 2019). "We observed that Dnmt3aR878H/+Npm1cA/+ MDS/MPD was associated with mutations in the tumor suppressor Cux1, previously shown to drive MDS and MDS/MPD and in the RNA splicing genes Rbm10 and U2af2." (PMID 30692594, 2019). "CUT-like homeobox 1 (CUX1) is a homeobox gene that is implicated in both tumor suppression and progression." (PMID 27835906, 2016). "The Cut homeobox 1 (CUX1) gene has been implicated in cancer as both a potential tumor suppressor and an oncogene." (PMID 24618719, 2014). "Furthermore, the findings of our study of the interstitial amplification within chromosome arm 7q, which was retained across all cell lines (including the 1° tumor cell line), CUX1 and its associated pathways emerged as important therapeutic targets." (PMID 36900209, 2023). "Indeed, rigorous pan-cancer gene-level analysis of copy number alterations and mutation patterns in primary patient samples reveal CUX1 genetic changes are significantly characteristic of a tumor suppressor gene." (PMID 34997000, 2022). "In PCa, the loss of CUX1 reduces the level of cellular senescence in tumor cells." (PMID 34879849, 2021). "It is worth mentioning that, although loss and/or inactivation of a CUX1 allele have been documented in many studies, there is so far no case of a tumor where both alleles have been lost or inactivated, suggesting the coexistence of an inactivated and an activated CUX1 alleles in tumor cells." (PMID 32547943, 2020).
tumor (continued). "However, a large scale genomic analysis of 7,651 diverse human cancers identified inactivating mutations in CUX1 in 1-5% of tumours and concluded that CUX1 acts as a tumour suppressor." (PMID 32180898, 2020). "More importantly, a comprehensive study by interrogating total 7,651 genome sequences derived from 28 tumor types revealed nonsense and frameshift mutations in CUX1 in 1–5% of tumors and found that CUX1 deficiency can lead to activation of the pro-oncogenic PI3K-AKT signaling." (PMID 32547943, 2020). "Among them, we revealed that miR-193a-5p could inhibit CRC migration and invasion via targeting tumor-associated genes like CUT-like homeobox 1 (CUX1) and intersectin 1 (ITSN1)." (PMID 33014778, 2020). "In addition to its physiological functions, CUX1 has been implicated in tumor development in many species including Drosophila, mouse, and humans." (PMID 32547943, 2020). "But recent findings showing that many types of tumors possess nonsense or frameshift mutations of CUX1 paradoxically suggest that p200 CUX1 may function as a tumor suppressor." (PMID 32547943, 2020). "Mechanistically, transcription factor p110 CUX1, a proteolytic product of p200 CUX1, promotes expression of glycolytic genes, while circ‐CUX1 facilitates EWSR1‐mediated MAZ transactivation to alter expression of p200 CUX1 and other genes associated with tumor progression." (PMID 31709724, 2019). "Increased CUX1 expression is associated with tumor progression." (PMID 27835906, 2016). "The Cut homeobox 1 gene, CUX1, has been implicated in both tumor suppression and tumor progression." (PMID 25682875, 2015). "The dual role of CUX1 in cancer is illustrated by the fact that most cell lines with CUX1 LOH display amplification of the remaining allele, suggesting that decreased CUX1 expression facilitates tumor development while increased CUX1 expression is needed in tumorigenic cells." (PMID 24618719, 2014). "On the one hand, CUX1 is located in the 7q22.1 chromosomal region, which is the target of loss-of-heterozygosity in a number of cancers, and recent studies have pointed to CUX1 being as the putative tumor suppressor on 7q22.1." (PMID 24618719, 2014). "Future experiments should verify whether CUX1 hemizygosity indeed causes an increase in mutations and DNA rearrangements that predispose cells to tumor development." (PMID 24618719, 2014). "Finally, the knockdown of Axin2 or β-catenin could reverse the tumor-promoting effects caused by CUX1 overexpression, suggesting that CUX1 induced gliomagenesis and malignant phenotype by activating the Wnt/β-catenin signaling pathway." (PMID 34422906, 2021). "Investigations on pancreatic neurosecretory tumors (pan-NET) have demonstrated that CUX1 serves as a prognostic marker post PanNET surgery and facilitates in vitro tumor progression through enhanced proliferation and angiogenesis." (PMID 39103807, 2024). "CUX1 presents a paradox in cancer research, embodying dual roles that complicate its classification as solely oncogenic or tumor-suppressive." (PMID 38659042, 2024). "Additional potential targets have been identified reported in the literature in the past years such as COX-2 and CUX1 which mediate tumor progression via cell proliferation and angiogenesis." (PMID 38375032, 2024). "For example, CUX1 acts as a tumor suppressor in many cancer types, including myeloid malignancies, inhibiting RAS- and PI3K-signalling and activating DNA repair." (PMID 38474011, 2024). "As a result, CUX1 reduces the recruitment and the activation of M1 TAMs, promoting tumor progression and angiogenesis in PDA." (PMID 38397187, 2024). "CircCUX1 interacted with EWS RNA binding protein 1 (EWSR1) to stimulate MYC-related zinc finger protein (MAZ) trans-activation, resulting in CUX1 transcription modification and other tumor progression-related genes being transcribed." (PMID 37091173, 2023). "It has been recently discovered that CUX1 is a tumor suppressor paradoxically overexpressed in tumor cells." (PMID 37214090, 2023).